SMARCA4 (SWI/SNF related BAF chromatin remodeling complex subunit ATPase 4)
Diseases named in the same sentence as SMARCA4 in open-access papers (continued):
Sharing a sentence is not in itself a finding about the gene and the disease.
undifferentiated sarcoma (4 papers, 2020 to 2025). "In summary, we have reported a case of SMARCA4-deficient undifferentiated sarcoma with rhabdoid/epithelioid features, arising from a pre-existing HFLT/PHAT of the foot." (PMID 34389899, 2022). "We describe a novel SMARCA4-deficient undifferentiated sarcoma with rhabdoid features originating from hybrid HFLT/PHAT in the foot of a 54-year-old male." (PMID 34389899, 2022). "Genetic alterations supporting the genetic diagnosis were identified in four of the five patients, including EWSR1-ATF1 in clear cell sarcoma, PTCH1-GLI1 in GLI1-rearranged tumor, SS18-SSX2 in synovial sarcoma, and SMARCA4-THOP1 in SMARCA4-deficient undifferentiated sarcoma." (PMID 34131151, 2021). "Furthermore, in the present study, we detected the novel SMARCA4-THOP1 fusion gene, which causes SMARCA4 biallelic inactivation, together with a point mutation in SMARCA4-deficient undifferentiated sarcoma." (PMID 34131151, 2021). "In addition to the SMARCA4-THOP1 fusion gene, RNA-seq also identified an SMARCA4 splice-site mutation (c.3168+1G>A), suggesting the diagnosis of SMARCA4-deficient undifferentiated sarcoma caused by biallelic inactivation of SMARCA424." (PMID 34131151, 2021). "Another rare differential diagnosis is SMARCA4-deficient thoracic sarcomas (SMARCA4-DTS), a recently described undifferentiated sarcoma that most commonly occur in the mediastinum of young-middle aged male smokers." (PMID 40641909, 2025). "We identified SMARCA4 inactivating alterations in an undifferentiated sarcoma in a 15-year-old girl." (PMID 34131151, 2021). "Additionally, we identified a novel fusion gene, SMARCA4-THOP1, in one patient with undifferentiated sarcoma (unique patient number [UPN] 66), which resulted in the truncation and subsequent loss-of-function of the SMARCA4 protein." (PMID 34131151, 2021).
uterine tumor (4 papers, 2012 to 2026). "The highest alteration frequency of SMARCA4 appears for patients with uterine tumors with “mutation” as the primary type." (PMID 34675941, 2021).
angiosarcoma (3 papers, 2023 to 2025). A malignant tumor arising from the endothelial cells of the blood vessels. "Angiosarcoma shows higher CD34 expression than SMARCA4-UT, expresses diffuse CD31 positivity, and typically exhibits endothelial multilayering." (PMID 38542211, 2024).
carcinosarcoma (3 papers, 2020 to 2025). A malignant tumor composed of a mixture of carcinomatous and sarcomatous elements. "The latest pathological research suggests that most teratoid carcinosarcomas are associated with SMARCA4 gene defects." (PMID 40860819, 2025).
epilepsy (3 papers, 2016 to 2023). A brain disorder characterized by episodes of abnormally increased neuronal discharge resulting in transient episodes of sensory or motor neurological dysfunction, or psychic dysfunction. "Interestingly, among multiple CRF genes, only SMARCA2, SMARCB1, ACTL6B and KDM5C have been previously associated with epilepsy, and some other members of this cluster (e.g., SMARCC1, SMARCC2, SMARCA4 and WRD5) are only cursorily mentioned among epilepsy candidate genes." (PMID 36982355, 2023). "Several genes which have been linked to cell death in cancer, epilepsy, or psychological disorders but not yet associated with brain injury, including CSNK2A1, ELAVL1, MITF, and SMARCA4, were also identified which may provide additional therapeutic targets for prevention of cell death following TBI." (PMID 26912237, 2016).
esophageal squamous cell carcinoma (3 papers, 2019 to 2024). Esophageal squamous cell carcinoma (ESCC) is a type of esophageal carcinoma (EC) that can affect any part of the esophagus, but is usually located in the upper or middle third. "Using CRISPR-Cas9 screening, we identify SMARCA4 as a novel dependency in SMARCA2-deficient esophageal squamous cell carcinoma (ESCC) models, reciprocal to the known synthetic lethal interaction." (PMID 31406271, 2019). "In contrast, SMARCA4 loss inhibits the growth of acute myeloid leukemia cells, melanoma, and SMARCA2-deficient esophageal squamous cell carcinoma (ESCC)." (PMID 36633435, 2023).
Fanconi anemia (3 papers, 2017 to 2025). Fanconi anemia (FA) is a hereditary DNA repair disorder characterized by progressive pancytopenia with bone marrow failure, variable congenital malformations and predisposition to develop hematological or solid tumors. "Most detected variants affected the Fanconi anemia/DNA repair pathway (34%, ATM, FANCA, FANCI, MLH1, MSH6, POLE, RAD51C, RAD51D) followed by mutations altering the SWI/SNF (SWItch/sucrose non-fermentable) complex (22%, ARID1A and SMARCA4)." (PMID 34200508, 2021).
large cell carcinoma (3 papers, 2017 to 2024). A malignant epithelial neoplasm composed of large, atypical cells. "In our cohort, all SMARCA4-dNSCLCs were poorly differentiated, and adenocarcinoma (59.6%) was the predominant histopathological type, followed by large cell carcinoma (15.4%)." (PMID 38374950, 2024).
neurofibromatosis (3 papers, 2020 to 2023). A hereditary neoplastic syndrome in which tumors grow in the nervous system. "Here, the authors report a rare case of a 2-year-old boy with a SMARCB1 (INI1) retained but SMARCA4 (BRG1) negative AT/RT arising at the bilateral cerebellopontine angles mimicking neurofibromatosis type 2." (PMID 34611487, 2021).
oligodendroglioma (3 papers, 2017 to 2023). A well-differentiated (WHO grade II), diffusely infiltrating neuroglial tumor, typically located in the cerebral hemispheres. "Recurrent oligodendroglioma patient mutations include M781I, T910M, R1192C/H and G1232S, again all located in the ATPase domain of SMARCA4 and bearing resemblance to mutations reported in MB." (PMID 37433987, 2023). "Multiple studies have reported recurrent SMARCA4 mutations in oligodendroglioma from patient data." (PMID 37433987, 2023). "Whilst missense SMARCA4 mutations observed in MB and oligodendroglioma have not been investigated in their native setting, they have been studied in human embryonic kidney cells." (PMID 37433987, 2023). "Though this finding is indirect and lacks a clear mechanism, it provides evidence that SMARCA4 may play an important regulatory role in oligodendroglioma tumourigenesis." (PMID 37433987, 2023). "However, when risk was assessed based on histological subtype, specific variants in SMARCA4 and SMARCA2 were correlated with a modest increase in risk of oligodendroglioma, but not astrocytoma or GBM." (PMID 37433987, 2023).
oral cancer (3 papers, 2014 to 2025). "We speculated that the early dissemination and metastasis of OSCC may be related to the driving mutations such as SMARCA4, CXCR4 and RUNX3, which provides a theoretical basis for the future study on the mechanism of early spread and metastasis of oral cancer." (PMID 36424557, 2022).
soft tissue tumor (3 papers, 2021 to 2024). "In the sinonasal tract, deficiencies of the subunits SMARCB1/INI1, SMARCA4/BRG1, and SMARCA2 have been noted in carcinomas, adenocarcinomas, and soft tissue tumors with a distinctive high-grade morphology and a fatal prognosis." (PMID 39590317, 2024). "In soft tissue neoplasms, SMARCB1 (INI1) is the subunit most frequently inactivated, followed by SMARCA4 (BRG1), and SMARCA2." (PMID 35125107, 2022).
teratoma (3 papers, 2015 to 2025). A non-seminomatous germ cell tumor characterized by the presence of various tissues which correspond to the different germinal layers (endoderm, mesoderm, and ectoderm). "The immature teratoma showed diminished expression of the BRG1 protein compared with normal tissues, thus it presumably retained one wt SMARCA4 allele." (PMID 25886974, 2015). "The presence of SMARCA4 alterations or BRG1 loss in immunohistochemistry has not been reported in teratomas." (PMID 39359021, 2025).
thoracic aortic aneurysm (3 papers, 2018 to 2022). An aneurysm formed in the wall of the proximal portion of the descending aorta proceeding from the arch of the aorta. "Studies have found that the expression of Smarca4 in the aortic middle layer of patients with thoracic aortic aneurysm (TAA) is significantly increased, and in human aortic VSMCs cultured in vitro, overexpression of Smarca4 can promote apoptosis and inhibit proliferation of VSMCs." (PMID 30973285, 2019).
thoracic cancer (3 papers, 2021 to 2025). A primary or metastatic malignant neoplasm affecting the tissues of the thorax. "BRG1 mutation leading to its loss of protein expression or LOF is found in ~10% of cases of NSCLC and is a key diagnostic defect in ~100% of cases of SMARCA4-DTS, a thoracic cancer." (PMID 41008934, 2025).
type 1 diabetes (3 papers, 2012 to 2025). "Higher SMARCA4 expression was significantly associated with increased risk of progression to type 1 diabetes (hazard ratio [HR] = 12.46, 95% confidence interval [CI]: 2.44–63.54, p = 0.002)." (PMID 41306972, 2025). "Participants with high expression of SMARCA4 at the time closest to, but after, the age of seroconversion had a significantly increased rate of progression to type 1 diabetes (p = 0.010)." (PMID 41306972, 2025). "Within protein– protein interaction (PPI) networks, we identified SMARCA4 as the central hub and found that its expression stratified progression to type 1 diabetes after seroconversion." (PMID 41306972, 2025). "A more in-depth analysis of hub genes revealed that the expression of SMARCA4, a DE gene, and RRAGA, a protein interactor included during PPI-network construction, stratified progression to type 1 diabetes after seroconversion." (PMID 41306972, 2025).
urothelial carcinoma (3 papers, 2019 to 2024). A malignant neoplasm derived from the transitional epithelium of the urinary tract (urinary bladder, ureter, urethra, or renal pelvis). "From these pathological observations, it is suggested that an undifferentiated tumor component with a SMARCA4 deficiency arose, in part, from a background of preexisting urothelial carcinoma, resulting in early retroperitoneal recurrence after TUR‐BT." (PMID 38923369, 2024). "Therefore, the patient was finally diagnosed with a retroperitoneal recurrence of a SMARCA4‐deficient undifferentiated urothelial carcinoma." (PMID 38923369, 2024).
acute leukemia (2 papers, 2019 to 2021). A clonal (malignant) hematopoietic disorder with an acute onset, affecting the bone marrow and the peripheral blood. "A critical requirement on SMARCA4 in promoting MYC-dependent transcription has been described in SMARCA2-proficient acute leukemia cell models." (PMID 31406271, 2019).
adenosarcoma (2 papers, 2017 to 2020). A low grade malignant neoplasm characterized by the presence of a benign epithelial component (tubular and cleft-like glands) and a low grade sarcomatous component that contains varying amounts of fibrous and smooth muscle tissues. "In addition, the Wnt signaling pathway was significantly altered in adenosarcomas, which harbored, among other alterations in Wnt pathway‐related genes, homozygous deletions of APC (1/19, 5%) and SMARCA4 (1/19, 5%) and nonsynonymous mutations affecting AXIN1 (1/19, 5%) and AXIN2 (1/19, 5%)." (PMID 28267263, 2017). "However, there have been no reports showing an association between adenosarcomas and SMARCA4 loss." (PMID 32972432, 2020). "Molecular testing, including for SMARCA4 and BCOR, might not be useful for predicting prognoses of adenosarcomas." (PMID 32972432, 2020).
alveolar rhabdomyosarcoma (2 papers, 2021 to 2024). A rapidly growing malignant mesenchymal neoplasm. "SMARCA4 has been found to be a unique factor in medium to long-term (but not short-term) tumor cell survival in alveolar rhabdomyosarcoma (ARMS), and ACBI-1 shows similar long-term tumor cell dependence in vitro and in vivo." (PMID 39697230, 2024).
bone cancer (2 papers, 2020 to 2023). A primary or metastatic malignant neoplasm affecting the bone or articular cartilage. "In bone tumors, the MSKCC cohort had significantly fewer mutations in MAP3K1, CREBBP, MCL1, GNAQ, MEF2B, MYCN, SDHA, and SMARCA4." (PMID 37546405, 2023).
brain cancer (2 papers, 2021 to 2023). A primary or metastatic malignant neoplasm affecting the brain. "SMARCA4 mutations observed in brain cancer are largely dependent on the type and clinical subgroup of the tumour, displaying diverse genetic interactions and functional consequences." (PMID 37433987, 2023). "SMARCA4 mutations in brain cancer predominantly occur in the crucial catalytic ATPase domain, which is associated with tumour suppressor activity." (PMID 37433987, 2023). "SMARCA4 mutations in brain cancer are well documented, however, less is known about how these mutations functionally alter BRG1 function on a molecular level to influence tumourigenesis." (PMID 37433987, 2023). "Overall, SMARCA4/BRG1 function and the genetic pathways it regulates are crucial to the underlying molecular mechanisms that are involved in brain cancer." (PMID 37433987, 2023). "Functional studies of SMARCA4 mutation in brain cancer models have been very limited." (PMID 37433987, 2023). "Thus, despite SMARCA4 functioning as a tumour suppressor in both of these brain cancers, the mechanism via which SMARCA4 mutation is involved in tumourigenesis may be unique and occur at different stages of tumour progression." (PMID 37433987, 2023). "Although SMARCA4 mutations were assessed in non-brain cancer cell lines, these studies provide hypothesis-generating results that suggest missense mutations may disrupt BRG1 function in brain cancer in a similar way and will inform brain cancer research in the future." (PMID 37433987, 2023). "We discuss developments made in targeting SMARCA4 and the potential to translate these to adjuvant therapies able to enhance current methods of brain cancer treatment." (PMID 37433987, 2023). "Whilst SMARCA2 inhibition has been demonstrated as a successful therapeutic strategy in SMARCA4-deficient cancer cell lines, its viability is yet to be confirmed in brain cancer cell lines where SMARCA4 is frequently inactivated." (PMID 37433987, 2023). "This review explores the multifaceted interaction between SMARCA4 and various brain cancer types, highlighting its roles in tumour pathogenesis, the pathways it regulates, and the advances that have been made in understanding the functional relevance of mutations." (PMID 37433987, 2023). "Whilst the SCCOHT cell line is a unique example that does not entirely reflect brain cancer, in brain cancer the SMARCA4 T910M mutation is primarily heterozygous and occurs in the presence of BRM expression, findings from this study reveal key mechanistic insights." (PMID 37433987, 2023). "Therefore, it is more likely that amplification of SMARCA4 is causing altered expression rather than missense mutations which appear to occur more sporadically in GBM than in other brain cancers." (PMID 37433987, 2023). "Interestingly, SMARCA4 amplification and overexpression were reported at a greater frequency in GBM compared to other brain cancer types." (PMID 37433987, 2023).
childhood cancer (2 papers, 2021 to 2023). "Somatic mutations in SMARCA4 are associated with childhood cancers, including Wilms tumors (4.5% prevalence)." (PMID 37727504, 2023). "SMARCA4 mutations are also associated with Wilms tumors, a type of renal cancers that accounts for nearly 90% of renal tumors in children and 7% of all childhood cancers." (PMID 37727504, 2023).
clear cell carcinomas (2 papers, 2018 to 2020). "This issue was directly explored by Conlan and coworkers who have screened a large set of ovarian cancers, showing that SMARCA4 loss was observed in 94% of SCCOHT samples, with the exception of a rare positivity (3%) in clear cell carcinomas." (PMID 29389895, 2018).
endometrial undifferentiated carcinoma (2 papers, 2022 to 2025). A primary carcinoma of the endometrium characterized by the presence of malignant cells that lack evidence of differentiation. "SMARCA2/BRM and BRG1/SMARCA4 are lost in approximately one-third of endometrial undifferentiated carcinomas." (PMID 35633893, 2022).
gynecologic cancers (2 papers, 2022 to 2025). "Patients with RTPS associated with gynecologic cancers are typically SMARCA4 deficient (RTPS2)." (PMID 35163487, 2022). "The loss of SMARCA4 (BRG1) and SMARCA2 (BRM) protein is pathognomonic for SCCOHT amongst other gynecologic cancers and histopathologic mimics." (PMID 39906560, 2025).
hereditary cancer (2 papers, 2019 to 2023). Malignant neoplasms occurring in families at a rate greater than that expected by chance and caused by germline mutations in a specific gene. "It is also interesting to highlight candidate genes involved in hereditary cancer (BRCA2, BLM, ERCC2, SMARCA4) or connected to inherited CRC, such as Cowden syndrome (SEC23B) and Peutz–Jeghers syndrome (STK11IP)." (PMID 30871259, 2019).
Hypercalcemia (2 papers, 2017 to 2024). An abnormally increased calcium concentration in the blood. "SMARCA4 immunohistochemistry should be included in the workup of neoplasms associated with hypercalcemia irrespective of gender and site." (PMID 29158936, 2017).
leiomyosarcoma (2 papers, 2023 to 2025). An uncommon, aggressive malignant smooth muscle neoplasm, usually occurring in post-menopausal women. "At the molecular level, leiomyosarcoma often has no SMARCA4 deletion mutation." (PMID 37194064, 2023).
myelodysplastic syndrome (2 papers, 2023 to 2024). A clonal hematopoietic disorder characterized by dysplasia and ineffective hematopoiesis in one or more of the hematopoietic cell lines. "Moreover, sequencing studies carried out on AML and/or myelodysplastic syndromes (MDS) have found recurrent deleterious mutations in SWI/SNF genes including ARID2, ARID1A and ARID1B, SMARCA2, and SMARCA4." (PMID 36941700, 2023).
Nephroblastoma (2 papers, 2023). An embryonal neoplasm characterized by the presence of epithelial, mesenchymal, and blastema components. "In this study, we investigated the impact of deleting the chromatin remodeling factor Smarca4 (Brg1), a human Wilms tumor-associated gene, in Wnt4-expressing cells." (PMID 37727504, 2023). "Overall, our findings highlight the critical role of Smarca4 in kidney development and the regulation of Pttg1 expression, providing new insights into the mechanisms underlying nephron tubule formation and renal disease, including Wilms tumor." (PMID 37727504, 2023).
olfactory neuroblastoma (2 papers, 2022 to 2023). An olfactory neuroblastoma arising in the paranasal sinus. "The neuroectodermal differentiation of specimens from the NEC-like IDH2 (FDR < 0.001) and NEC-like SMARCA4/ARID1A class (FDR < 0.001) as well as olfactory neuroblastomas (FDR < 0.001) was reflected in their similarity with pulmonary neuroendocrine cells (PNEC)." (PMID 36443295, 2022). "In contrast, cytokeratin 18 (KRT18) was strongly overexpressed in both NEC-like IDH2 and NEC-like SMARCA4/ARID1A cancers but not in olfactory neuroblastoma." (PMID 36443295, 2022).
ovarian undifferentiated carcinoma (2 papers, 2021 to 2026). "Histopathologic examination demonstrated a FIGO stage IA low-grade endometrioid carcinoma of the uterine corpus and a SMARCA4-deficient undifferentiated carcinoma of the ovary." (PMID 41906161, 2026).
pancreatic ductal adenocarcinoma (2 papers, 2023). An infiltrating adenocarcinoma that arises from the epithelial cells of the pancreas. "For example, it was shown that Brg1 (SMARCA4) inhibits dedifferentiation of pancreatic acinar cells prior to their neoplastic transformation while promotes proliferation of pancreatic ductal adenocarcinoma cells by maintaining mesenchymal-like gene expression." (PMID 37345003, 2023).
prostate adenocarcinoma (2 papers, 2020 to 2023). "Most recently, two studies demonstrated that SMARCA4 was required for growth of prostatic adenocarcinoma cells, as also confirmed by our results." (PMID 33144576, 2020). "The expression of SMARCA4 is low in esophageal carcinoma (ESCA), prostate adenocarcinoma (PRAD), and skin cutaneous melanoma (SKCM)." (PMID 37217462, 2023).